LDHA (lactate dehydrogenase A)
Diseases named in the same sentence as LDHA in open-access papers (continued):
Sharing a sentence is not in itself a finding about the gene and the disease.
tumor (continued). "It has been reported that LDHA can mediate tumor immune escape by inhibiting the activity of T cells and NK cells." (PMID 33413205, 2021). "Further investigation of the expression levels of LDHA in tumor tissues, its relation with serum LDH, and the clinical significance is warranted." (PMID 33777804, 2021). "More importantly, the effect of LINC00671 knockdown on tumor growth was markedly abrogated when LDHA was knocked down." (PMID 34404767, 2021). "It implied that PlGF was involved in modulating tumor growth by modulating protein expression of β-catenin, C-myc, and LDHA." (PMID 33407494, 2021). "Neither kPL nor AUCL/P were significantly correlated with blood lactate levels or tumor LDHA or MCT1." (PMID 33925445, 2021). "Our results concerning the prognostic value of lactate are consistent with previous findings that LDHA expression in tumour tissue and serum lactate dehydrogenase from ccRCC patients are associated with survival." (PMID 34822422, 2021). "Comparatively, eliminating LDHA at the level of the germline gives rise to T cell progeny with limited anti-tumor function suggesting the temporal regulation of LDH activity is an essential consideration for adoptive immunotherapies." (PMID 34203136, 2021). "An HIF1-a target is LDHA, which converts pyruvate to lactate and is highly expressed in tumor cells because of its high glycolytic activity." (PMID 33923299, 2021). "LDHA overexpression also remodels tumor microenvironment with activated HIF-1 signaling pathways, which is associated with resistance to radiotherapy and results in poorer clinical outcomes." (PMID 33902615, 2021). "LDHA catalyzes lactate production, and glycolysis is one of the basic characteristics of tumor cell metabolism." (PMID 34853310, 2021). "Flow cytometry analysis revealed a decrease population of Treg cells in LDHA knockout xenograft tumor, while exogenous lactate significantly increased the number of Treg cells." (PMID 34482375, 2021). "Deleting LDHA in specific tumors reverses immunosuppression in the tumor microenvironment, likely through reduced PD-L1 and VEGF." (PMID 33718271, 2021). "By real-time qPCR analysis, we found that CD73 knockdown can lead to significant down-regulation of glycolytic genes (GLUT1, HK2, ENO1, and LDHA) in tumor tissues from the subcutaneous xenograft model." (PMID 34659527, 2021). "It was also reported that the high expression of LDHA was related to tumor volume, stage, and degree of cell differentiation and affected the disease-free survival (DFS) and overall survival (OS), which is an important indication for clinical diagnosis." (PMID 34307169, 2021). "According to our studies both MCT1, MCT4 and LDHA are increased in patient tumor samples, compared to normal tissue." (PMID 33668151, 2021). "Squamous epithelial cells of tumour tissues showed significantly higher LDHA staining than normal tissues." (PMID 34743698, 2021). "Enhanced glycolysis through upregulation of lactate dehydrogenase A (LDHA) in the tumor microenvironment is another finding on SNHG7 overexpression, which can help the cancer cell economy." (PMID 35111760, 2021). "The down regulation of LDHA protein by Fraction B in Panc-1 tumor tissues was further confirmed by Western blot analysis." (PMID 34349642, 2021). "Activation of Wnt/β-catenin pathway advances tumor progression by promoting transcription of C-myc which directly regulates LDHA." (PMID 33407494, 2021). "Annexin A2 isoform 2 (ANXA2) has been reported to play an important role in tumor migration and invasion, and L-lactate dehydrogenase A chain (LDHA) and PKM1 have both been reported to be closely related to tumor glycometabolism." (PMID 33495406, 2021). "We observed that LDHA expression levels were significantly downregulated whereas PGC‐1α expression levels were upregulated in tumour tissues from the baicalein and TAM + baicalein treatment groups." (PMID 34841716, 2021).
tumor (continued). "The exploration of the biological function of LDHA suggested that the inhibition of LDHA suppressed tumor growth in vitro and in vivo, which is consistent with the findings of the previous studies." (PMID 33795650, 2021). "In this study, the HIF-2 antagonist PT2399 was used to observe the expression of HIF-2 downstream proto-oncogenes (VEGF, LDHA, etc.)in tumor cells." (PMID 34604067, 2021). "LDHA, one of the key enzymes, catalyzes the final step of glycolysis and promotes the efficiency of glycolysis in tumor cells and reduces their dependence on oxygen." (PMID 34404767, 2021). "LINC00671 suppresses PTC tumor growth and metastasis through inhibition of LDHA-mediated Warburg effect." (PMID 34404767, 2021). "LDHA has a key role in tumor cell metabolism and adaptation to unfavorable environmental or cellular conditions." (PMID 34463208, 2021). "In mouse models of lung cancer, targeting LDHA significantly inhibited tumorigenesis and tumor progression." (PMID 33795650, 2021). "Lactate dehydrogenase A (LDHA) provides energy for tumor metabolism by promoting glycolysis to transform pyruvate into lactic acid." (PMID 34659642, 2021). "We recently found that PGC1β regulates tumor growth and metastasis through a lactate dehydrogenase A (LDHA)-mediated glycolytic metabolism, as well as through the expression of SREBP1-mediated hexokinase domain component 1 (HKDC1)." (PMID 33423158, 2021). "Lactate dehydrogenase A (LDHA) is a metabolic enzyme that can produce lactate in human body, and it has become an important indicator of clinical tumor diagnosis." (PMID 33413205, 2021). "In a triple-transgenic mouse model of PCa, knockdown of LDHA slowed primary tumor growth and development of metastases, implicating LDH activity and lactate production in progression of PCa." (PMID 33652703, 2021). "Tumour sections were stained for Ki-67, Bax, phospho-AMPKα (Thr172), LDHA, cleaved caspase 3 and H&E staining." (PMID 33139797, 2021). "As expected, the glycolytic inhibitor 2-DG and knockdown of LDHA, the enzyme that catalyzes the final step of glycolysis, inhibited tumor growth." (PMID 34482375, 2021). "The results in both ST and IHC analyses revealed that LDHA expression in the tumor boundary in both groups was higher than that in the tumor center." (PMID 34086429, 2021). "Among the genes associated with shorter survival in PPS20, TRIO, LDHA, MAP4K4 and ARNTL2 contribute to cellular motility/invasiveness/tumor aggressiveness and thus can also be contributing to shorter event-free survival." (PMID 32310997, 2020). "LDHA is known to be elevated in a variety of tumour cells and plays an important role in tumour development and maintenance." (PMID 32391634, 2020). "Collectively, we found that BEV monotherapy leads to a more acidic tumor microenvironment characterized by increased LDHA and lactate levels." (PMID 32641990, 2020). "LDHA in skeletal muscle is an energy-metabolizing enzyme critical for tumor-related anaerobic respiration." (PMID 32947951, 2020). "The increased production of lactic acid by lactate dehydrogenase A (LDHA) is found to impair the production of IFN-γ in tumor-infiltrating T cells and inhibits immunosurveillance, thereby contributing to tumor growth." (PMID 33298096, 2020). "LDHA expression and lactic acid production by tumor cells correlates with suppression of TIL effector function, likely as a result of the poor lactate efflux and resulting intracellular acidification that interferes with NFAT expression in T cells." (PMID 32508018, 2020). "Knockdown of LDHA in tumor cells induces increased mitochondrial respiration, decreased proliferation and suppressed tumorigenicity." (PMID 33173435, 2020). "More specifically, LDHA has been found to promote upregulation of PD-L1 on tumor cells, impeding effector T cell activity." (PMID 31932876, 2020).
tumor (continued). "And the altered expressions of LDHA, enolases play a potential role in tumorigenesis as tumor cells possess a higher metabolic rate than the normal tissues." (PMID 33207819, 2020). "The sustained TVN alleviates tumor hypoxia, reduces LDHA and lactate productions, and creates a sustained window of opportunity to improve chemotherapy efficacy." (PMID 32641990, 2020). "Apart from WDR1, several other oncoproteins and tumour suppressors, such as LDHA, CLIC1, ARPC5, ZYX, RCN1, FHIT and CFTR, were identified in this study." (PMID 32601462, 2020). "Du and his partners disclosed that miR-26b exerted its tumor suppressive role through the modulation of glycolytic metabolism in OS cells, showing as regulating expression of glycolytic components, LDHA and GLUT-1." (PMID 32190006, 2020). "The IHC staining results also confirmed that the protein levels of HIF1A and LDHA were higher in tumor tissues, than in normal tissues." (PMID 32152275, 2020). "Lactate accumulation resulted from continuous activation of glycolytic and LDHA enzymes leads to a low-pH microenvironment during tumor progression." (PMID 32211335, 2020). "In vivo interference with LDHA in B16.F10 tumors or administration of IL-33 to tumor-bearing mice increased the number of intratumoral ILC2 and restored ILC2 ability to contrast tumor progression." (PMID 33329534, 2020). "In the present case, low FDG uptake and weak expression of Glut-1, HK-2, and LDHA were observed in tumor tissue, suggesting low glycolytic activity in PLNTY." (PMID 32811569, 2020). "HIF-1α accumulation contributes to glycolysis by enhancing transcription of glycolysis-related genes, including GLUT1, HK2, ALDOA, PKM2, and LDHA, which was the most important method for tumor cells to get energy and growth." (PMID 33244454, 2020). "Lactate dehydrogenase A plays a major role in tumor acidity by converting pyruvate to lactic acid in tumor cells." (PMID 33298099, 2020). "Tumor suppressive role of miR-34a was first discovered during a study on c-Myc, LDHA, and SIRT1 oncogenes." (PMID 32440325, 2020). "Such bioenergetics changes are in agreement with several findings that examined the impact of LDHA depletion in tumor cells by FX11 inhibition or LDHA gene knockdown." (PMID 32034005, 2020). "Several studies have reported that LDHB is constitutively expressed in various cancer cell types, while LDHA is proposedly important for tumor initiation as it is often overexpressed in cancer." (PMID 33199724, 2020). "It was reported that delivery of siRNAs targeting lactate dehydrogenase A by cationic lipid-assisted nanoparticles in 4T1 mammary tumor-bearing mice neutralizes tumor pH, elicits infiltration of CD8+ T and NK cells and impedes the growth of tumors." (PMID 33298099, 2020). "Malignant tumor tissue of premenopausal women showed significantly higher protein expression of LDHA concomitant with lower protein expression of LDHB." (PMID 33353120, 2020). "For example, lactate dehydrogenase A (LDHA) is overexpressed in different cancers, and LDHA inhibition is shown to impair tumorigenesis and tumor growth." (PMID 32572027, 2020). "Lactate dehydrogenase A (LDH-A) expression has influence on the tumor microenvironment through HIF signaling, and the immune response is modulated via expression levels of hexokinase 1 and 2 (HK 1 and 2) and VEGF secretion." (PMID 32300553, 2020). "While in CCRCC, upregulated-ATP citrate lyase (ACLY)-mediated fatty acid synthesis and lactate dehydrogenase A (LDHA)-mediated glycolysis provided ATP for CCRCC tumor cells growth." (PMID 32127786, 2020). "Targeting lactate dehydrogenases, in particular LDHA, offers another lucrative approach to alter the balance in tumor metabolic needs and to shape the composition and orientation of the immune microenvironment." (PMID 33324565, 2020). "As LDH-A is known to play a key role in tumor growth, knockdown with LDHA siRNA decreased cell proliferation, colony formation activity, and lactate production activity." (PMID 33072745, 2020).
tumor (continued). "We also observed that dual therapy reduces the production of BEV-induced lactate and LDHA expression, remodeling a less acidic tumor microenvironment." (PMID 32641990, 2020). "The effect of K222-succinylated LDHA on tumor growth and metastasis was evaluated by in vitro and in vivo experiments." (PMID 32859246, 2020). "Dual treatment with TEPP-46 and FX-11 resulted in increased PK and reduced LDHA enzyme activity in plasma and tumor tissues and decreased PKM2 and LDHA expression in tumors, which was reflected by a decrease in tumor volume and proliferation." (PMID 31527446, 2019). "RT-qPCR analysis of LDHA mRNA levels in 25 OSCC tumor tissues and 15 ANCTs revealed that LDHA mRNA levels were elevated in the tumor tissues of patients with OSCC." (PMID 31921691, 2019). "Upregulated LDHA expression is characteristic for rapidly growing cells, and inhibition of LDHA expression impairs vascularization and suppresses tumor cell growth." (PMID 31471554, 2019). "Taken together the phosphorylated-induced activation of LDHA provides other mechanism used by tumor cells in order to establish a malignant phenotype." (PMID 31737570, 2019). "Overexpression of LDHA promotes tumor cell malignant transformation and growth, indicating the important role of LDHA in tumor initiation or maintenance." (PMID 31850189, 2019). "A high level of LDHA correlates with poor patient survival rates, greater tumor size, its histological grade, advanced clinical stage, Gleason scores and relapse of disease." (PMID 31035592, 2019). "LDHA catalyzes the last step of aerobic glycolysis, which is highly critical to the glycolysis phenotype of tumor cells." (PMID 31850189, 2019). "PKM2 detection and LDHA expression were considerably lower in tumor sections from all treatment groups compared with controls." (PMID 31527446, 2019). "Our results showed that the inhibition of LDHA activity by MA treatment reduced lactate and ATP production under normoxic and hypoxic conditions, leading to the suppression of tumor growth in vitro and in vivo." (PMID 31324019, 2019). "Elevated levels of LDHA in tumor cells are considered as their metabolic adaptation to anaerobic glycolysis." (PMID 31035592, 2019). "At the same time, the formation of lactic acid from pyruvate is facilitated by the HIF-1α-mediated upregulation of LDHA, which contributes to the acidification of the tumor microenvironment." (PMID 31078780, 2019). "This compound also suppressed the growth of tumor cells in in vitro and in vivo experiments by regulating LDHA activity." (PMID 31324019, 2019). "PDT-BIPA can inhibit LDHA in HL-60 cells in a concentration- and time-dependent way leading to the burst of ROS and metabolic changes to suppress cancer cells and tumor in vitro and in vivo, respectively." (PMID 31835667, 2019). "Inhibition of LDHA and LDHA short hairpin ribonucleic acid (shRNA) induced oxidative stress, inhibited tumor progression, and suppressed tumor-initiating cell survival and proliferation." (PMID 31324019, 2019). "We further examined the role of LDHA on OSCC tumor formation in vivo through subcutaneous injections of HSC3 cells into the inner thighs of NOD/SCID mice." (PMID 31921691, 2019). "Gossypol, also known as AT-101, is an LDHA inhibitor that has shown significant anti-tumor effects in various types of tumor cells." (PMID 31027222, 2019). "It was previously reported that lactate produced by LDHA in cancer cells is a potent inhibitor of the function and survival of T and Natural killer (NK) cells, leading to tumor immune evasion." (PMID 31324019, 2019). "One of the other ways through which LDHA promotes tumor progression is by regulating cancer stem cell markers and a positive correlation between LDHA expression and CSC/EMT markers has been noted." (PMID 31146503, 2019). "Inhibition of LDHA reduces malignant transformation and delays tumor formation, indicating an important role for LDHA in tumor initiation and progression." (PMID 30688660, 2019).
tumor (continued). "Efficacy was validated in vivo by evaluating tumor growth, PK and LDHA activity in plasma and tumors, and PKM2, LDHA, and Ki-67 expression in tumor tissues following treatment." (PMID 31527446, 2019). "From these results, we conclude that PSTMB can provide an alternate option for inhibiting LDHA activity and for targeting glucose metabolism as an anti-tumor strategy." (PMID 30850682, 2019). "While on the contrary, mRNA levels of HK2 and LDHA genes were elevated in tumor tissues formed by Wnt3-pEX4 cells." (PMID 31632267, 2019). "Studies indicated LDHA is responsible for tumor initiation evidenced by reduction of LDHA reduced cellular transformation and markedly delayed tumor formation." (PMID 31835667, 2019). "The results of immunohistochemistry staining showed that the number of LDHA and Ki67 positive cells decreased significantly in tumor from nude mice injected with NDRG2-overexpressing HepG2 cells compared with the control groups." (PMID 31523182, 2019). "Four enzymes from glycolysis were included: hexokinase (HK1), phosphoglucose isomerase (PGI), phosphofructokinase (PFKM), pyruvate kinase (PKM2, the major isoform in tumours) and lactate dehydrogenase (LDHA)." (PMID 30655616, 2019). "For instance, in murine tumor models, the myeloid-specific knockout of lactate dehydrogenase-A (LDH-A) or the reduction of lactate production by diclofenac exposure reduced the T cell immunosuppression and increased antitumor immunity." (PMID 31129755, 2019). "LDHA activity is typically increased in various cancer cells, and tumor hypoxia catalyzes the conversion of pyruvate and NADH to lactate and NAD+." (PMID 31324019, 2019). "The downregulation of LDHA expression is related to the upregulation of estrogen-related receptor alpha, leading to changes in the oxidative metabolic profile of the tumor." (PMID 29629339, 2018). "LDHA silencing in HCT116 cancer cell line resulted in apoptosis of the cancer cells, which indicates the significance of LDHA in tumor growth and progression." (PMID 29568375, 2018). "LDHA executes the final step of aerobic glycolysis and has been reported to be involved in tumour progression." (PMID 30559929, 2018). "As a consequence of glycolysis, hypoxic tumor cells upregulate LDHA and convert pyruvate into lactic acid, which results in increased tumor acidosis." (PMID 30061885, 2018). "We identified novel XAV939-induced proteins, including gelsolin (a possible tumor suppressor) and lactate dehydrogenase A (a key enzyme of glycolysis), which were differentially expressed between 2D- and 3D-cultured SW480 cells." (PMID 30185973, 2018). "We found that the A-498 tumors had significantly higher 13C pyruvate-to-lactate conversion than the UOK262 and 786-O tumors, with a corresponding trend in the tumor LDHA expression." (PMID 30189677, 2018). "Glycolytic targets of tyrosine kinase signaling include PGAM1, PKM2, and LDHA where phosphorylation of each of these enzymes promotes increased glycolytic rate and increased tumor cell proliferation." (PMID 30087897, 2018). "An oncogene such as c-myc is activated by tumor cells and up-regulates the expression of lactate dehydrogenase A (LDH-A) and promotes the conversion of pyruvate to lactic acid." (PMID 30477520, 2018). "For tumors with higher cellularity per given volume of tumor, the observed hyperpolarized 13C pyruvate-to-lactate conversion is expected to reflect both the cellular metabolism (i.e., LDHA mediated pyruvate to lactate conversion) as well as cellularity." (PMID 30189677, 2018). "Dynamic HP 13C pyruvate MRI showed that the A498 tumors had significantly higher 13C pyruvate-to-lactate conversion than the UOK262 and 786-O tumors, corresponding to higher A498 tumor LDHA expression." (PMID 30189677, 2018). "Although the isoforms of LDH are expressed in several tissues, LDHA is upregulated in a wide range of tumor tissues." (PMID 29629339, 2018).